RETN (resistin)
Diseases named in the same sentence as RETN in open-access papers (continued):
Sharing a sentence is not in itself a finding about the gene and the disease.
Obesity (continued). "We have shown that resistin, a pro-inflammatory hormone secreted by murine adipocytes, was increased in the adipose tissue of our MHO model following 12 weeks of HFD feeding compared with atherosclerotic ApoE-/- mice and classical obesity diet-induced obesity WT mice." (PMID 30369883, 2018). "Given links of obesity to PTS2,10,14,15 and experimental data on the impact of adipokines on prothrombotic mechanisms in various models, we conducted a prospective cohort study to assess a predictive value of resistin, adiponectin and leptin in the PTS development." (PMID 29720688, 2018). "Mechanistically, the obesity-related inflammation includes mTOR, JAK, JNK, IKKβ, and PI3K/Akt signaling pathways involved in inflammation activation, which contribute to increased secretion of cytokines, such as TNF-α, IL-6, and resistin, and decreased secretion of adiponectin." (PMID 28182687, 2017). "Differences in resistin levels were detected but there was no clear relationship between their concentration and obesity degree, lower levels than the Ctrl group were found in ObI group(1162.9 pg/mL) and the highest levels were detected in ObII/III group(1722.8 pg/mL)." (PMID 28425473, 2017). "Ten biochemical parameters related to diabetes and obesity were measured by a multiplex kit: c-peptide, ghrelin, glucose-dependent insulinotropic polypeptide (GIP), glucagon-like peptide-1 (GLP-1), glucagon, insulin, leptin, plasminogen activator inhibitor-1 (PAI-1), resistin and visfatin." (PMID 28915840, 2017). "Our results demonstrate that tomato and broccoli extract treatment regulates glucose homeostasis via reduction of serum resistin and may be a useful non-pharmacological therapy for obesity." (PMID 27430475, 2016). "It indicates circulating resistin levels may not be a predictor of obesity-related cancers at least in the USA." (PMID 27509174, 2016). "As a result, increasing evidence links human resistin with the chronic low-grade sub-clinical inflammation that accompanies obesity rather than the adipose deposits itself, with a high level of macrophage infiltration seen in the adipose tissue of obese individuals." (PMID 26097512, 2015). "Both serum and hepatic resistin had a correlation with obesity, but not with insulin resistance." (PMID 24559185, 2014). "Therefore, our results suggest that resistin is not an etiological link between obesity and diabetes." (PMID 23776497, 2013). "Several studies have shown increased expression of resistin in abdominal adipose tissue of obese individuals which correlates with the severity of obesity and insulin resistance, while others failed to confirm any impact of obesity and insulin resistance on the concentrations of resistin." (PMID 23691290, 2013). "Plasma resistin levels in relation to obesity are not as clear as those for adiponectin." (PMID 24109426, 2013). "Resistin expression has been analysed in rodent models of obesity and diabetes, suggesting that it is not clear if serum resistin levels in obesity genetic models (ob/ob and db/db) as well as in a diet-induced model of diabetes and obesity are elevated or decreased." (PMID 21760816, 2011). "In our SP and MO patients, as well as in prior studies of septic patients, resistin did not correlate to obesity measured by BMI which suggests that in circumstances of critical illness the release of resistin by macrophages plays a superior role compared with the secretion from adipocytes." (PMID 20825686, 2010). "As concluded above, resistin is not expressed in human primary adipocytes but it is present in immune cells which are found in subcutaneous WAT in obesity and also infiltrate epicardial fat depot in patients with coronary disease independent of BMI and diabetes." (PMID 17183659, 2006).
Obesity (continued). "In addition, the role of resistin in human obesity has also produced conflicting reports, and at present resistin still remains controversial as a potential mediator in the pathogenesis of T2DM and the impact of resistin on T2DM status." (PMID 15998471, 2005). "However, a negative correlation of serum resistin with hip circumference was noted, supporting a possible link between resistin and obesity." (PMID 15998471, 2005). "Furthermore, several studies, though not all, have reported increased serum resistin levels in patients with obesity, insulin resistance, and/or type 2 diabetes." (PMID 15578112, 2004). "The study of resistin and visfatin offers not just deeper insights into the intricate interplay between obesity and cancer but also serves as a reminder that every molecule in our body harbors a story waiting to be told—a story that could potentially revolutionize medicine." (PMID 40040878, 2025). "Furthermore, resistin can differentiate children with obesity and with or without hepatopathy." (PMID 39519480, 2024). "Regarding the fact that IR, obesity, and inflammation are of critical importance in the development and progression of NAFLD, and resistin plays an important role in these metabolic disorders, it is biologically reasonable to hypothesize that RETN gene may be involved in NAFLD pathogenesis." (PMID 39045929, 2024). "Furthermore, the inference that RETN is involved in the interaction among obesity, insulin resistance and low‐grade inflammation has been challenged because human adipocytes have not been demonstrated to secrete RETN and that RETN in humans is mainly secreted by monocytes." (PMID 37060578, 2023). "What’s more, one of the biological explanations for obesity negatively affects the progression of periodontitis and the response to periodontal therapy may be also due to the unaffected leptin, resistin and adiponectin levels after the periodontal non-surgical treatment." (PMID 37231396, 2023). "For that purpose, group of 45 children with obesity (OB) and group of 45 age‐matched children without obesity (CG) were examined in terms of serum levels of miR‐27a and biochemical parameters: fasting blood glucose, adiponectin, leptin, resistin, subfatin, visfatin, and TNF‐α, IL‐6." (PMID 34918493, 2022). "However, some studies have shown high values of serum resistin in women with breast cancer independent of BMI, different from what was observed in the present study, in which obesity was a determining factor for hyperresistinemia, which is enhanced in the presence of the tumor." (PMID 32903534, 2020). "Although present in gross visceral fat deposits in humans, resistin is a component of inflammation, being released from infiltrating white blood cells of the sub-clinical chronic low grade inflammatory response accompanying obesity, rather than from the adipocyte itself." (PMID 26097512, 2015). "In the present study,we examined whether resistin TNF-α, IL-6, and IL-1β mRNA levels from human peripheral mononuclearcells are altered in type 2 diabetes and whether they correlate withcirculating resistin levels and with indices of obesity or insulin resistance." (PMID 19125180, 2008). "Despite the well-known connection between obesity and chronic subclinical inflammation, we did not observe a significant reduction in the studied inflammatory markers (ferritin, IL-6, TNF- α resistin, PAI-1) following the treatment with submaximal GLP-1 RA." (PMID 41011232, 2025). "More specifically, in a study of children with obesity with and without NAFLD, resistin correlated with SGOT, SGPT and γ-GT." (PMID 39519480, 2024). "Serum leptin, resistin, PAI-1, and CRP levels differed significantly between children with normal body weight and those with overweight/obesity, and between those with and without MetS (all p<0.05), being higher in children with overweight/obesity and MetS." (PMID 36920931, 2023).
Obesity (continued). "However, our understanding about the link between overweight and obesity and metabolic syndrome has increased with the discovery of various products released from adipocytes, such as inflammatory cytokines, leptins, non-esterified fatty acids, adiponectin, and resistin." (PMID 35512304, 2022). "Consistent with the reduction of obesity, treatment of KY19334, but not orlistat, specifically improved their metabolic parameters including total cholesterol, HDL-cholesterol, leptin, and resistin as well as the blood glucose level and insulin sensitivity." (PMID 36450849, 2022). "HF+FO/E, but not HF+FO/D, was able to prevent the changes triggered by obesity in TNF-α, Il-10, and resistin secretion in ING and RP depots." (PMID 33652751, 2021). "and resistin mRNA expression in adipose tissue was significantly higher in subjects with PWS, compared with both healthy lean controls and subjects with obesity and without PWS." (PMID 33891302, 2021). "The adipokines, resistin and leptin were increased in mice induced to obesity by the HFD, while eriocitrin at 10, 25 and 100 mg/kg was able to moderately reduce resistin, but not leptin." (PMID 33489104, 2020). "Here, we evaluate the serum levels of resistin in female dogs with or without mammary carcinoma in mixed tumors (CBMT) and its correlation with the proliferative potential of the tumor, obesity, and survival." (PMID 32903534, 2020). "Although we could not identify the underlying mechanism or the link among resistin, leptin, and CD163/CD68 expression levels, our data suggest that serum resistin levels and leptin levels have specific roles in the regulation of ATM in patients with modest obesity." (PMID 27101398, 2016). "Plasma resistin levels between moderate and severe OSA even in slight degrees of obesity – (BMI – 28) do not reach statistically important difference." (PMID 23497617, 2013). "Interestingly, in children with obesity with or without NAFLD, resistin demonstrated a positive correlation with HDL." (PMID 39519480, 2024). "However, in a different study, leptin levels decreased in subjects with overweight or obesity who followed an ADF protocol, but adiponectin levels did not change, nor did other biomarkers of inflammation, including resistin, IL-6, or TNF-α." (PMID 36364915, 2022). "The increased resistin and follistatin levels in PCOS patients were independent of obesity status." (PMID 33740002, 2021). "In addition, obesity significantly increased plasma TNF-α, PAI-1 and resistin levels in ApoE-/- mice but not in ApoE-/-TSP1-/- mice." (PMID 25803585, 2015). "Resistin mRNA expression is increased in PBMC from DM2 women, together with increased expression of the inflammatory cytokines IL-1β, TNF-α, and IL-6, independent of obesity." (PMID 19125180, 2008). "Beyond the role of renal function as a major determinant of resistin levels in our as well as in other studies, our hypothesis is that in our cohort, resistin levels are similar in women with and without T2DM, because of a similar degree of dysfunctional obesity, which is not captured by BMI values." (PMID 34496965, 2021). "Thus, the interaction between insulin and resistin we observed in the rats fed the HFD occurs within the brain even in the absence of overt obesity, suggesting that high fat diets can influence the pathways mediating the changes in RSNA even in the absence of overt obesity." (PMID 30804811, 2019).
Insulin resistance (711 papers, 2004 to 2026). Increased resistance towards insulin, that is, diminished effectiveness of insulin in reducing blood glucose levels. "Resistin, an adipokine associated with insulin resistance and inflammation, has been found to decrease after omega-3 supplementation in rodent and human tissues, although results are variable depending on the dose and model." (PMID 41334336, 2025). "Concurrently, adiponectin expression, known for its anti-inflammatory properties and ability to enhance insulin sensitivity, was increased, whereas resistin expression, an adipokine linked to insulin resistance and inflammatory processes, was suppressed." (PMID 40733199, 2025). "A logistic regression model was developed to assess the risk of insulin resistance using resistin, TMAO, and their interaction as predictors." (PMID 40077669, 2025). "Elevated plasma resistin levels, commonly associated with insulin resistance, are also strongly linked to increased CRC risk, particularly in rectal cancer patients, where resistin correlates significantly with insulin levels (r = 0.881)." (PMID 40243559, 2025). "Conversely, resistin, an adipokine associated with insulin resistance and type 2 diabetes, can disrupt insulin signaling." (PMID 41378205, 2025). "Resistin (RETN) is a cytokine produced by adipose tissue involving in glucose and lipid metabolism, which is known to be associated with inflammation and insulin resistance." (PMID 40641746, 2025). "Resistin, originally identified as an adipokine implicated in insulin resistance and glucose metabolism by regulating inflammation, has emerged as a multifaceted factor with far-reaching implications for human health." (PMID 39983655, 2025). "Emerging adipokines such as resistin, chemerin, visfatin, omentin, and lipocalin-2 have been linked to regulating inflammation, insulin resistance, and neuroimmune interactions." (PMID 40725107, 2025). "Further perpetuating metabolic dysfunction, this aging-associated insulin resistance and inflammation also triggers the release of pro-inflammatory adipokines, particularly resistin, by adipocytes and macrophages." (PMID 41315571, 2025). "Resistin, another adipokine, has been associated with metabolic disorders, including insulin resistance, type 2 diabetes, and atherosclerotic cardiovascular disease." (PMID 40040878, 2025). "It is strongly linked to insulin resistance, chronic low-grade inflammation, and the dysregulation of adipokines such as adiponectin and resistin, which in turn contribute to atherogenic dyslipidaemia." (PMID 40662131, 2025). "Adiponectin is an adipokine that has anti-inflammatory and insulin-sensitizing properties, while resistin is another adipokine that antagonizes the action of insulin, causing glucose intolerance; increased resistin is associated with insulin resistance." (PMID 41441034, 2025). "Multimarker panels incorporating resistin alongside adipokines and insulin resistance markers outperform resistin alone in predicting cardiovascular disease risk." (PMID 41347124, 2025). "In contrast, resistin is a pro-inflammatory adipokine related to cardiovascular risk factors and insulin resistance." (PMID 40013194, 2025). "Elevated resistin levels are strongly linked to insulin resistance, as they impair insulin signaling, increase hepatic glucose production, and reduce peripheral glucose uptake, contributing to hyperglycemia and metabolic syndrome." (PMID 40077669, 2025). "Recombinant human resistin causes insulin resistance via both the AMPK (AMP-activated protein kinase)-dependent and AMPK-independent suppressor of cytokine signalling-3 (SOCS-3) signalling pathways." (PMID 40216734, 2025). "Among these, leptin, adiponectin, CRP, TNF-α, and resistin are closely associated with the occurrence and development of insulin resistance." (PMID 40302954, 2024).
Insulin resistance (continued). "In Chinese subjects, visceral fat mass was always high, but adipokines (adiponectin and resistin) were diversely associated with insulin resistance." (PMID 39469144, 2024). "Initially linked to insulin resistance and inflammation, high levels of resistin have been associated with various obesity-related diseases, including diabetes, cardiovascular disease, and several cancers." (PMID 39184804, 2024). "Its action is associated with the development of insulin resistance, and the inhibition of resistin activity lowers serum glucose levels and increases insulin sensitivity, which has favorable clinical significance." (PMID 38794651, 2024). "Elevated levels of resistin increase the risk of developing cardiovascular disease and insulin resistance." (PMID 38892118, 2024). "Single nucleotide polymorphisms in human RETN are associated with altered plasma resistin levels, dyslipidemia, and insulin resistance, particularly in East Asian populations." (PMID 38238841, 2024). "Resistin was positively associated with insulin levels in CRC, whereas blockade of resistin by antibodies resulted in a decrease in blood glucose levels and insulin resistance." (PMID 39184804, 2024). "The ECS induces resistin expression in the CB1R-positive human peripheral monocytes that infiltrate into the target tissues associated with insulin resistance and inflammation." (PMID 39050819, 2024). "25(OH)D deficiency promotes the development and progression of NAFLD by causing insulin resistance, increasing hepatic resistin gene expression, and upregulating hepatic steatosis and oxidative stress gene expression." (PMID 38982394, 2024). "The association between resistin and insulin resistance in humans remains controversial because human resistin is secreted by monocytes and macrophages rather than adipocytes as in mice." (PMID 39050819, 2024). "One such candidate biomarker is resistin, a proinflammatory cytokine primarily produced by adipocytes and implicated in the regulation of insulin resistance and glucose metabolism." (PMID 38562275, 2024). "On the other hand, adipokines such as leptin and resistin, known for their pro-inflammatory characteristics, have been linked to elevated cardiac lipid deposition, insulin resistance, and fibrosis." (PMID 39538244, 2024). "A high resistin concentration is associated with insulin resistance, so it can be indicated that the proposed interventions led to favorable changes in a population characterized by metabolic disorders, including carbohydrate metabolism disorders." (PMID 38794651, 2024). "The adverse effects of VAT are likely due to its profile of adipokine secretion including interleukin, tumour necrosis factor-α, and resistin, which are all associated with insulin resistance and diabetes." (PMID 38297029, 2024). "The serum resistin of mice in the M group increased, which promoted insulin resistance and caused inflammation." (PMID 37569125, 2023). "Resistin is a cytokine that is produced by white adipocytes and has been implicated in the development of insulin resistance and other metabolic disorders." (PMID 37238961, 2023). "The adipokine resistin has been linked to T2D, and has thus been suggested in recent years as a preclinical marker of insulin resistance." (PMID 36833129, 2023). "High concentrations of resistin and leptin and low concentrations of adiponectin are associated with insulin resistance." (PMID 36922815, 2023). "Serum resistin—and chemerin concentrations were positively associated with insulin resistance-markers, including insulin, FBG and HOMA-IR (p < 0.0001)." (PMID 36830883, 2023). "Another study found that high levels of resistin in the bloodstream are linked to the development of HF, even after taking into account the presence of existing coronary heart disease, obesity, insulin resistance, and inflammation." (PMID 38058391, 2023).